TFE3 (transcription factor binding to IGHM enhancer 3)
Diseases named in the same sentence as TFE3 in open-access papers (continued):
Sharing a sentence is not in itself a finding about the gene and the disease.
papillary renal cell carcinoma (20 papers, 2011 to 2025). A rare subtype of renal cell carcinoma, arising from the renal tubular epithelium and showing a papillary growth pattern, which typically manifests with hematuria, flank pain, palpable abdominal mass or nonspecific symptoms, such as fatigue, weight loss or fever. "While TFE3 has been implicated in papillary renal cell carcinomas, to the best of our knowledge, its role in breast cancer has not been reported." (PMID 36950380, 2023). "Other common fusion genes are papillary renal cell carcinoma-TFE3 (PRCC-TFE3), t(X;1)(p11.2;q21.2) and PTB-associated splicing factor-TFE3 (PSF-TFE3), t(X;1)(p11.2;p34)." (PMID 30458744, 2018). "The TFE3 gene was found to be fused with the papillary renal cell carcinoma (PRCC) gene on chromosome 1q21.2 [PRCC-TFE3 t(X;1)(p11.2;q21)]." (PMID 34660181, 2021). "Additionally, translocations of the Xp11.2 region involving TFE3 have been reported in up to 30–50% of pediatric papillary renal cell carcinoma cases." (PMID 32881934, 2020). "The fusion of either NonO or SFPQ with the TFE3 transcriptional factor has been observed in papillary renal cell carcinoma." (PMID 38248868, 2024). "According to the 2016 WHO classification, non-clear cell carcinoma consists of papillary renal cell carcinoma, nephroblastoma and Xp11.2 translocations/TFE3 gene fusion in our study." (PMID 31992244, 2020). "TFE3 is involved in chromosomal translocations that result in various gene fusions (such as PRCC-TFE3, RCC17-TFE3, PSF-TFE3, NONO(p54nrb)-TFE3 and ASPL-TFE3) in papillary renal cell carcinomas." (PMID 26684754, 2015).
renal tumors (20 papers, 2010 to 2025). "Here we show, using murine disease‐relevant models as well as BHD‐associated renal tumors, that both TFEB and TFE3 play important roles not only in the kidney cystic phenotype but also in human renal tumor formation." (PMID 36987696, 2023). "The study reinforces the importance of using a multidisciplinary diagnostic approach, and the application of markers such as TFE3, PAX8, and CA IX helps confirm the diagnosis and also delineates it from other renal tumors." (PMID 39851801, 2025). "Among kidney tumors with TFE3 gene translocations, most are morphologically heterogeneous carcinomas positive for the immunohistochemical nuclear tubular marker PAX8." (PMID 39410016, 2024). "TFE3 fusions were actually pinpointed in alveolar sarcomas of the soft parts, which share many morphological features with these renal tumors." (PMID 34680535, 2021). "In general, whenever possible, young patients diagnosed with renal tumors should benefit from genetic counseling and testing (Chromophobe-RCC is associated with Birt-Hogg-Dubé syndrome, 10% of clear-cell RCC harbor Xp11.2/TFE3 translocation)." (PMID 32517346, 2020). "The mechanisms leading from TFE3/TFEB gene overexpression to kidney tumor development remain largely uncharacterized, thus the need for modeling these diseases in experimental animal systems for the identification of effective targeted therapies." (PMID 27668431, 2016). "The most common renal neoplasms that mimic TFE3 RCCs are those with clear cells and papillary architecture." (PMID 26415891, 2015). "Because of the small number of TFE3 gene fusion-related renal tumors described in the literature, the exact biologic behavior and impact of current treatment modalities remain to be uncertain." (PMID 24455396, 2013). "We examined GPNMB expression as a readout of TFE3 transcriptional activity in the renal tumors from BHD patients." (PMID 21209915, 2010). "TFE3-fusions are known to drive both epithelial and mesenchymal renal tumors." (PMID 41044182, 2025). "However, there is considerable phenotypic heterogeneity in renal tumors driven by different TFE3-fusion proteins, in part due to varying functions of the fusion partners, underscoring a need to develop fusion-specific models to study the disease." (PMID 41044182, 2025). "In this review, we analyzed the clinicopathologic and molecular data of TFE3-rearranged renal tumors reported in the English literature, proposing our perspective on the findings that could help resolve this emerging conundrum." (PMID 39410016, 2024). "We next further examined whether such localization pattern of TFE3 also occurred in kidney tumor samples." (PMID 36935008, 2023). "This hypothesis fits with the observation that renal tumors specifically driven by TFE3 activation behave more aggressively as compared to slowly growing BHD tumors." (PMID 33459596, 2021). "Remarkably, the analysis of BHD patient‐derived tumor samples revealed increased activation of TFEB/TFE3‐mediated transcriptional program and silencing either of the two genes rescued tumorigenesis in human BHD renal tumor cell line‐derived xenografts (CDXs)." (PMID 36987696, 2023). "Increased TFE3 activity is a downstream event induced by FLCN inactivation and is likely to be important for renal tumor development." (PMID 21209915, 2010). "Furthermore, the high severity of the renal cystic phenotype of kidney‐specific Flcn KO mice leads to early lethality, before the development of kidney tumors, thus hampering the evaluation of the role of TFEB/TFE3 in kidney tumorigenesis." (PMID 36987696, 2023). "In accordance with the TFE3 staining pattern, GPNMB expression was restricted to renal tumor cells and was absent from embedded normal renal tubules (bottom left)." (PMID 21209915, 2010).
sarcoma (19 papers, 2011 to 2026). A usually aggressive malignant neoplasm of the soft tissue or bone. "Examples of antibodies serving as surrogate markers of sarcoma-specific genetic aberrations, e.g., fusions, amplifications, and point mutations, include SS18-SSX or SSX, TFE3, SMARCB1, BCOR, MDM2, DDIT3, and PAX3." (PMID 40526340, 2025). "Like other sarcoma-associated fusion genes, ASPSCR1::TFE3 is essential for transforming target cells to induce ASPS in vivo." (PMID 37029109, 2023). "It’s also hypothesized that the nuclear localization and activation of MITF/TFE3, caused by V-ATPase dysfunction, might contribute to GCT development, as TFE3 gene fusions and the nuclear presence of resulting fusion proteins are seen in various sarcomas." (PMID 39372871, 2024). "Transcription Factor E3 (TFE3) is a member of the MiT/TFE family of transcription factors and is involved in the pathogenesis of several sarcoma subtypes through gene rearrangement." (PMID 33921435, 2021). "Altogether, cross-species comparison of transcriptome, methylome, and histology data revealed a coherent picture, indicating conservation of human sarcoma biology across the sarcoma EPO-GEMM cohort, especially for bona fide fusion-driven sarcomas SS18::SSX, NTRK-Mono, PAX3::FOXO1 and ASPSCR1::TFE3." (PMID 40523919, 2025). "It is also possible that MITF/TFE3 nuclear localization and activation due to V-ATPase dysfunction contributes to GCT tumorigenesis, since TFE3 gene fusions and nuclear localization of the resulting fusion proteins are observed in several types of sarcomas." (PMID 37958362, 2023).
clear cell renal cell carcinoma (16 papers, 2017 to 2025). "Previous studies have reported that LINC02747 can upregulate the expression of TFE3 by absorbing miR-608 and ultimately promote the proliferation of clear cell renal cell carcinoma (ccRCC)." (PMID 35529472, 2022). "To further validate the database information, we examined 30 clinical renal clear cell carcinoma samples by qPCR and confirmed that TFE3 expression is higher." (PMID 33145941, 2020). "Likewise, the proliferative defects induced by MITF knockout in an MITF-driven renal clear cell carcinoma model was restored by transfecting TFE3, indicating that MITF and TFE3 may have partially redundant roles in regulating proliferation and survival." (PMID 32881934, 2020).
soft part sarcoma (13 papers, 2010 to 2025). "Immunohistochemical staining exhibited nuclear or nuclear/cytoplasmic TFE3 staining in the tumor cells from BHD patients although the intensity was not as strong as in the t(X;1)(p11.2;q21) translocation alveolar soft part sarcoma involving TFE3." (PMID 21209915, 2010). "In addition, it was recently shown that in alveolar soft part sarcoma, the expression of the fusion transcription factor ASPSCR1::TFE3 is required for in vivo tumor development via angiogenesis, orchestrating higher-ordered angiogenesis via super-enhancers activity." (PMID 37510264, 2023).
pancreatic cancer (10 papers, 2019 to 2025). "While TFE3 IHC has been considered a specific diagnostic protein assessment for SPN, recent studies have reported TFE3 expression in other pancreatic tumors, with positivity rates of up to 14.3% in PDAC and 23.5% in PanNET, significantly limiting its diagnostic specificity." (PMID 41310888, 2025). "Interestingly, and in agreement with the effects of HMT on PP2A methylation and activity, this treatment clearly reduced nuclear accumulation of MITF and TFE3 in pancreatic cancer cells." (PMID 37996408, 2023). "The result showed TFE3 had significant distribution to the nucleus in 11 of 12 samples, which was significantly higher than lung cancer tissues and at least comparable with pancreatic cancer from the same database." (PMID 36935008, 2023). "Notably, TFEB and TFE3 expression levels are increased in pancreatic cancer, compared with normal pancreatic tissues." (PMID 36746928, 2023). "Thus, TFE3 can be useful along with beta catenin as a diagnostic marker for SPN and in differentiating it from other pancreatic neoplasms." (PMID 33298094, 2020). "Similarly, upregulation and increased nuclear residence of Tfe3 sustain pancreatic tumor growth." (PMID 31544066, 2019). "We therefore investigated the expression of MITF, TFE3, and TFEB by immunohistochemistry (IHC) across pancreatic tumor types." (PMID 41310888, 2025). "Moreover, TFE3 has been validated as an oncogene in kidney and pancreatic cancers by virtue of its regulation of metabolic and non-metabolic pathways." (PMID 33987007, 2021). "This is consistent with our finding that MITF and TFE3, upstream transcription factors of lysosome-related genes, are overexpressed in SPN, but not in four other pancreatic tumor types (PDAC, PanNET, ACC, and PBL) or benign pancreatic tissues." (PMID 41310888, 2025). "As observed in these figures, the lack of PP2A activity in pancreatic cancer cells clearly resulted in a reduction of nuclear MITF and TFE3, while significantly increased cytoplasmic retention of both proteins." (PMID 37996408, 2023).
breast carcinoma (7 papers, 2020 to 2026). "As expected, lysosomal gene mRNA levels were positively correlated with TFEB and TFE3 levels and negatively correlated with MYC and TET2 levels in breast cancer patients (normal-like tumors, n = 639)." (PMID 35351824, 2022). "We also knocked down TFE3 and TFEB in lung cancer and breast cancer cells where their expression has no negative correlation with patient prognosis and it was found that alteration of the TFE3 or TFEB expression has little effect on tumour maintenance or progression (data not shown)." (PMID 33145941, 2020).
lung carcinoma (7 papers, 2020 to 2025). "It was found that the inhibition of PLK4 in TFEB and TFE3 double-knockout cells drastically reduced the proliferation of lung cancer cells, providing a rationale for combination therapies." (PMID 41488365, 2025). "It shows that there is a new and much more important pathway, namely, pAMPKα, which upregulates the activities of Brf1 and Pol III genes to promote human lung cancer development except AMPK-mediated Tfe3." (PMID 33995823, 2021). "Recently, it was shown that lung cancer initiation was dependent on AMPK‐induced TFE3 nuclear translocation and lysosome biogenesis." (PMID 33665961, 2021). "Additional gene fusions have also been identified in other vascular and lung cancers involving YAP, TFE3 (transcription factor E3), WWTR1, NF2, LATS1 and LATS2." (PMID 34831354, 2021).
lymph node metastasis (7 papers, 2016 to 2024). "Clinical information such as age and lymph node metastasis are independent risk factors, which can be used as a supplement to the results of TFE3 IHC." (PMID 38477529, 2024). "However, in our model, age, gender, IHC, and lymph node metastasis were key risk factors for the TFE3‐rearranged RCC." (PMID 38477529, 2024). "High expression levels of TFE3 were closely associated with lymph node metastasis." (PMID 34660181, 2021). "Age, gender, lymph node metastasis, and IHC were the most significant predictors of TFE3‐rearranged RCC." (PMID 38477529, 2024). "The results indicated that high expression of TFE3 was significantly correlated with lymph node metastasis (P < 0.05)." (PMID 34660181, 2021). "TFE3 nuclear expression was also found to be even higher in lymph node metastasis (n = 5, P < 0.01)." (PMID 26872381, 2016). "Of note, compared with other TFE3-tRCC subtypes, tumors with ASPSCR1-TFE3 fusion were highly aggressive, characterized by higher ISUP nuclear grade (ISUP ≥ 3, 11/13 vs. 19/44, P = 0.017) and more frequent lymph node metastasis (6/13 vs. 7/44, P = 0.057)." (PMID 34489456, 2021). "The study showed that the high expression of TFE3 was significantly correlated with lymph node metastasis, which reflected the possible relationship between lymph node metastasis and autophagy-lysosome levels in PTC patients." (PMID 34660181, 2021).
Obesity (7 papers, 2017 to 2024). Accumulation of substantial excess body fat. "Recent studies have revealed that Tfe3 knockout (KO) mice exhibit abnormal mitochondrial metabolism, abnormalities in systemic glucose and lipid metabolism, and an increased risk of obesity and diabetes induced by a high-fat diet." (PMID 36906611, 2023). "It was reported that the TFE3 protein could promote fatty acid catabolism and mitochondrial function to reduce the risk of obesity, implying that the TFE3 fusion protein could drive a unique energy metabolic signature in TFE3 rRCC." (PMID 37770905, 2023). "TFE3 depletion enhances diet‐induced obesity and diabetes, while its overexpression has the opposite effects." (PMID 28283651, 2017). "In line with the severe obesity, in vivo‐stimulated lipolysis was impaired in Tfe3 KO mice (Fig EV3K)." (PMID 28283651, 2017). "Both TFEB overexpression in Tfe3 KO mice and TFE3 overexpression in Tcfeb liver‐specific KO mice (Tcfeb LiKO) rescued HFD‐induced obesity, indicating that TFEB can compensate for TFE3 deficiency and vice versa." (PMID 28283651, 2017). "Previous studies have revealed that obesity may affect RCC risk through multiple mechanisms, and adipose tissue appears to regulate TFE3-RCC risk." (PMID 38261736, 2024). "Moreover, in vitro studies have confirmed that adiponectin can inhibit tumor growth by activating AMP-activated protein kinase (AMPK) and inhibiting the mammalian rapamycin target (mTOR) pathway, validating the role of obesity in TFE3-RCC." (PMID 38261736, 2024). "Strikingly, TFEB overexpression is also able to rescue obesity in Tfe3 KO mice." (PMID 28283651, 2017). "In addition, Tfe3 KO mice showed significant abnormalities in energy balance and alterations in systemic glucose and lipid metabolism, resulting in enhanced diet‐induced obesity and diabetes." (PMID 28283651, 2017). "CR increased transcripts of both TFE3 and FNIP2 in Control females only, while Obesity prevented the CR-induced increases." (PMID 38166559, 2024). "Indirect calorimetry showed a significant increase in RER (VCO2/VO2) values indicating a preferential utilization of carbohydrates and reduced lipid catabolism in Tfe3 KO mice fed with a HFD, which explains the obesity‐prone phenotype." (PMID 28283651, 2017). "Indeed, 8 weeks of exercise training failed to improve obesity, endurance capacity and glucose homeostasis in Tfe3 KO mice." (PMID 28283651, 2017). "Importantly, Tfe3 KO mice showed down‐regulation of genes involved in thermogenesis, including Ucp1 and Ucp3, and oxidative genes such as Pparα in the BAT, which account, at least partially, for their reduced energy expenditure and diet‐induced obesity." (PMID 28283651, 2017). "Thus, the absence of TFE3 in mice results in enhanced diet‐induced obesity and diabetes, indicating that TFE3 plays an important role in lipid metabolism, metabolic homeostasis and in the adaptive response to dietary lipids." (PMID 28283651, 2017). "FInally, the increase in TFE3 mRNA is not necessarily indicative of increased TFE3 activity; reliable antibodies for phosphorylated TFE3 in mouse were not available to us for this study, but would provide valuable information for future studies for how TFE3 behaves due to obesity and sex." (PMID 38166559, 2024).
clear cell carcinoma (6 papers, 2020 to 2025). "ASPS has a characteristic molecular phenotype, which helps to distinguish it from other diseases such as TFE3 translocation-associated PEComa and clear cell carcinoma." (PMID 40176092, 2025). "Among the 26 patients with RCC, 20 (76.9%) had Xp11.2 translocations/TFE3 gene fusion, 3 had papillary carcinoma, 2 had clear cell carcinoma, and 1 had chromophobe cell carcinoma." (PMID 35733141, 2022). "Studies have reported that the imaging examinations may differentiate TFE3‐rearranged RCC from clear cell carcinoma." (PMID 38477529, 2024). "Immunostaining of the tumor revealed hepatocyte, arginase 1, CK20, CD10, CA9, and TFE3 negativity, along with AE1/AE3 and CK7 positivity, leading to the diagnosis of clear cell carcinoma of the liver." (PMID 41018392, 2025).
granular cell tumor (6 papers, 2015 to 2025). An unusual benign or malignant neoplasm characterized by the presence of neoplastic large polygonal cells with granular, eosinophilic cytoplasm which contains abundant lysosomes. "A heads-on comparison of staining between ASPS and granular cell tumors showed TFE3 expression in 91% of granular cell tumors." (PMID 38393424, 2024). "Only in six other cases in their series was a strong or moderate expression of TFE3 observed (two adrenal cortical carcinomas, two granular cell tumors, one bile duct carcinoma, and one myxofibrosarcoma;)." (PMID 31309284, 2020). "Granular cell tumor and solid pseudopapillary neoplasm of pancreas also express TFE3 stain with no associated genetic abnormalities." (PMID 35225876, 2022).
metastatic disease (6 papers, 2009 to 2023). "In terms of overall expression level, MITF had a 4- and 15-fold higher mRNA expression than that of TFEB and TFE3, respectively, in the metastatic tumors (Sup." (PMID 30705290, 2019). "In fact, TFE3 negatively correlates with the expression of melanosomal genes in the metastatic tumors, indicating a specific role for MITF in regulating melanosomal genes." (PMID 30705290, 2019). "This case clearly correlated the presence of metastatic disease with the microscopic appearance of TFE3 overexpression resulted from TFE3 rearrangement and copy number gain." (PMID 27733182, 2016). "Other than TFE3 positivity and primary metastatic disease, the other variables that correlated with worse OS in the univariable analysis were receiving two lines of therapy (HR: 14.4, 95% CI: 2.3–90.0, P = 0.004), malignant PEComa histology (HR: 8.1, 95% CI: 1.0–65.3, P = 0.05)." (PMID 37448552, 2023).